GZMB (granzyme B)
Diseases named in the same sentence as GZMB in open-access papers (continued):
Sharing a sentence is not in itself a finding about the gene and the disease.
tumor (continued). "Further analysis of the tumor lysates indicated that V-Navo@gel could elevate pro-inflammation cytokines (IL12 and IFNγ) and granzyme B, the marker of activated T cells, at the tumor site, indicating the elevated anti-tumor immune responses against tumors." (PMID 37296221, 2023). "Our results indicated that the CD4+ CTL subset expressed PRF1, GZMA, and GZMB, indicating that CD4+ CTLs may induce apoptosis in tumor cells via the release of cytotoxic mediators, especially granzyme B and perforin." (PMID 38077321, 2023). "The functional mechanisms of NK-exos increase high tumor cell-killing effects including cytotoxic and apoptotic activity through the cytotoxic proteins, including perforin and granzyme B, trigger the caspases activation-dependent apoptosis pathway in cancers [26,37,50,]." (PMID 37484408, 2023). "Moreover, to evaluate the killing effect of CTLs on TYST, the levels of GPC3 and granzyme B expression were also determined by IHC in tumor tissues." (PMID 37986544, 2023). "Notably, in the TME, IFN-γ can act as a cytotoxic cytokine, along with perforin and granzyme B, inducing apoptosis in tumor cells." (PMID 37766179, 2023). "CD8+ T cells can kill tumour cells by secreting large amounts of interferon-γ, tumour necrosis factor α and protease granzyme B. Therefore, CD8+ T cells compete for a very important role in anti-tumour immunity and are considered to be associated with a better prognosis for malignant tumour." (PMID 37815881, 2023). "In TME, IFN-γ orchestrates both pro-tumorigenic and antitumor immune responses, acting as a cytotoxic cytokine together with granzyme B and perforin to hit tumor cells, but also triggering the synthesis of inhibitory immune checkpoints thus stimulating immune-suppressive mechanisms." (PMID 36854895, 2023). "GNR could deliver an immune checkpoint inhibitor (e.g., anti-programmed death-ligand 1 (PD-L1) antibody) to the highly immunogenic tumor, inducing the release of granzyme B to turn “On” the fluorescence of GNR for real-time imaging of immunotherapy response." (PMID 37513233, 2023). "GzmB remains high in ILTCKs during late-stage tumor growth, suggesting resistance to exhaustion." (PMID 37892995, 2023). "Moreover, both CD3+/CD8+ CTLs and CD3+/CD56+ NKT cells killed tumor cells in cell contact-dependent and -independent manners via granzyme B and interferon-γ/TNF-α, respectively." (PMID 37100864, 2023). "Notably, granzyme B expression was significantly higher on CD8+ TRM cells in the tumor center in SCC compared to ADC." (PMID 37448786, 2023). "However, the percentage of CD8+ T cells per tumour surface area and extent of granzyme B (GrzB) expression was comparable to that of untreated tumours." (PMID 37287625, 2023). "Whereas T/P or Taz treatment alone increased T cell infiltration into PDAC tumors, single agent treatment did not cause NK cell mobilization or enhanced immune cytotoxicity (as marked by GZMB expression), and resulted in only marginal changes in tumor growth and overall survival of KPC GEMM animals." (PMID 37142692, 2023). "In the lung tumors from VC-induced mice, the percentage of CD8+ tumor-infiltrating lymphocytes (TILs) was significantly increased upon PV-1 treatment, and the production of granzyme B, TNF-α and IFN-γ by CD8+ cells were all significantly increased in these mice." (PMID 38077406, 2023). "In addition, overexpression of DSE promoted the overexpression of tumor killer molecules such as GZMB, TNF and IFNG in CD8 + T cells, and inhibited the expression of inhibitory molecules such as PD-1, TIM-3 and LAG-3." (PMID 37833287, 2023). "A study found that they could lyse immune cells via the perforin–granzyme B pathway and stipulated that this mechanism could be co-opted to kill tumor cells." (PMID 37754534, 2023). "Therefore, tumor-derived EVs containing CD73 can inhibit granzyme B and INF-γ synthesis in Tc cells." (PMID 37175226, 2023).
tumor (continued). "Confocal analysis showed that murine and human CD8+ TILs that had been cultured with IμHABcl6-FRCs or DLBCL-FRCs(p), respectively, displayed a reduced ability to form F-actin–rich, granzyme B+ (GrB) lytic synapses with tumor B cells when compared with FRC-educated TILs." (PMID 37219943, 2023). "In this study, we investigated whether granzyme B (GZMB) in the tumor microenvironment can be a biomarker of therapeutic response and prognosis in TNBC via the immunohistochemical staining of clinical specimens from 230 patients with primary TNBC." (PMID 37760424, 2023). "In keeping with these findings, the EOAI3402143 treatment alone or combination with anti-CTLA-4 significantly reduced the PD-1 protein abundance in tumor-infiltrating CD3+ T cells and enhanced the production of IFN-γ, TNF, and GzmB in tumor-infiltrating CD8+ T cells compared with control treatment." (PMID 37208329, 2023). "Granzyme B and perforin, which are expressed in cytotoxic T cells, were expressed in both the iγδTs and PBγδT cells, suggesting that the iγδTs, like authentic γδT, directly attach to and attack tumor cells with lytic granules carried by secretory lysosomes." (PMID 36963392, 2023). "In contrast, GZMB+-activated pDCs effectively kill tumor cells." (PMID 37817484, 2023). "R848@M2pep-MPsAFP significantly increased the numbers of CD4+ T cells, activated CD4+CD69+ T cells, CD8+ T cells, proliferated CD8+ T cells and activated CD8+CD69+ T cells, CD8+IFNγ+ T cells and CD8+GzmB+ T cells in tumor tissues compared with free R848, R848@MPs, R848@M2pep-MPs and R848@MPsAFP." (PMID 37704614, 2023). "Whereas N803 in combination with vaccine promoted circulating activated CD8+ T cells with augmented expression of the trafficking chemokine receptor CXCR3, CD8+ T cells showed poor tumor infiltration and granzyme B expression in the TME, resulting in modest antitumor efficacy." (PMID 37371081, 2023). "Meanwhile, the numbers of CD8+ T cells, proliferative CD8+ T cells, activated CD8+ T cells, stem-like CD8+ T cells, terminally exhausted CD8+ T cells and terminally exhausted CD8+ T cells secreting GzmB in tumor tissues were the highest in R848@M2pep-MPsOVA and anti-PD-1 antibody-treated group." (PMID 37704614, 2023). "Granzyme A, Granzyme B, perforin, the fas ligand, trail, and IFN were upregulated as a result of these CD8+ effector memory T cells migrating to a distal tumor, which caused cytotoxic effects and inhibited the growth of the distal tumor." (PMID 37507972, 2023). "Most of these CD8+ TILs in ccRCC are exhausted, i.e., they are not capable of killing tumor cells, and one mechanism for this exhaustion phenotype is the loss of the effector protein granzyme B." (PMID 37894418, 2023). "Recent studies indicated that activated γδT cells could release granzyme B and perforin to trigger anticancer immunity, thereby counteracting tumor development." (PMID 36878969, 2023). "Consequently, combination treatment increased the number of CD8+ T cells, with elevated activation marker (granzyme B), as well as reduced regulatory T cells (Tregs) in tumor tissues." (PMID 37880243, 2023). "R848@M2pep-MPsAFP treatment also significantly increased the numbers of the activated CD8+CD69+ T cells, CD8+IFNγ+ T cells and CD8+GzmB+ T cells in spleens of orthotopic Hepa1-6 tumor-bearing mice, suggesting that R848@M2pep-MPsAFP efficiently activated the systemic antitumor immunity." (PMID 37704614, 2023). "Similarly, the hypoxic nature of the TIME drives upregulation of LDHA in CD8+ tumor-infiltrating lymphocytes (TILs), leading to excess intracellular lactic acid, which then inhibits IFNg and granzyme B production and T cell expansion." (PMID 37842241, 2023). "Furthermore, the intracellular levels of both perforin and granzyme B in tumor infiltrated CD8+ T cells increased notably after the combined treatment." (PMID 37720226, 2023).
tumor (continued). "In addition to inducing effector Th1 cells, CXCL10 can also recruit CXCR3+CD8+T cells to the tumor site and promote these cells to produce Granzyme B, which enhances the anti-tumor effect." (PMID 36900218, 2023). "Moreover, their anti-tumor activity was further confirmed by the presence of granzyme B+ and IFNγ+ staining in CD8+ T cells from responders." (PMID 36707872, 2023). "However, simultaneously, they share the same MOAs; one is cell contact-dependent (direct) tumor cell killing via granzyme B, and another one is cell contact-independent (indirect) tumor cell killing via IFN-γ and TNF-α." (PMID 37100864, 2023). "In addition, co-culturing of CD8+ T cells with tunicamycin pre-treated Ero1aKO tumor cells showed significant increase in the release of IFN-γ, TNF-α, and GzmB compared with controls, indicating that tumor ERO1A induces T cell dysfunction." (PMID 37769655, 2023). "Immunohistochemical staining of FAK-/- and FAK-/-STAT3shRNA tumour sections using an anti-CD8 antibody also confirmed the infiltration of CD8 T-cells within the tumour mass, while an anti-granzyme-B antibody showed positive intratumoural staining indicative of ongoing CD8 T-cell activity." (PMID 36977556, 2023). "Moreover, tumors from Usp5 cKO mice treated with Trametinib displayed reduced PD-1 expression and elevated IFN-γ, TNFα, and GzmB in tumor-infiltrating CD8+ T cells." (PMID 37208329, 2023). "Additionally, the percentage of tumor-infiltrating GzmB+CD8+ T cells among CD8+ T cells was significantly increased, suggesting that CTLs functioned to kill tumor cells." (PMID 36641456, 2023). "Even with the low levels of IL-12 released by activated T cells, we observed along with the increased production of pro-inflammatory cytokines, such as IFN-γ and TNF, the enhanced expression of GzmB, which is a major effector molecule of T cells for inducing apoptosis in tumor cells." (PMID 36793716, 2023). "In this system, therapeutic proteins, including perforin and granzyme B that could efficiently lyse tumor cells and promote tumor cell apoptosis, were encapsulated in acid-degradable ZIF-8 through a co-precipitation method." (PMID 36593957, 2023). "In this study, we examined whether GZMB in the tumor microenvironment can be a biomarker for treatment response and prognosis in TNBC." (PMID 37760424, 2023). "Moreover, Tfh cells produce IL-21, which increases antitumor immunity by promoting the expression of IFN-γ and granzyme B in tumor-infiltrating CD8+ T cells." (PMID 36776832, 2023). "Secondly, we quantified release of cytokines (i.e., IFNγ, IL-10, IL-2, IL-6, TNFα, GM-CSF, IL-12p70, IL-1b and IL-8) and granzyme B by using the MSD platform in supernatants collected from the TDCC assay with the tumor cell lines SK-CO-1, MKN-45 and H2122 after 48 h." (PMID 38087365, 2023). "Furthermore, incubation with tumor cells expressing the cognate antigen increased GzmB expression in CD8 T cells, especially in Foxp3UP CD8 T cells." (PMID 36045586, 2023). "Granzyme B (GZMB), a main member of a family of serine proteases, is also a toxic granule secretase produced by cytotoxic T lymphocytes and natural killer cells in the tumor microenvironment." (PMID 35464869, 2022). "Tumor growth was described to be repressed due to the disruption the fibrotic-like ECM, which led to improved infiltration of CD8+ T cells and the production of granzyme B, therefore improving anti-tumor immunity and response to immunotherapy in tumor-bearing mice." (PMID 36119516, 2022). "Upregulation of immune checkpoint proteins, such as PD-1, CTLA-4, and T-cell immunoglobulin mucin-3 (TIM-3), and of transcripts IL8 and CXCL12, concomitant with downregulation of granzyme B and perforin in tumor MAIT cells, indicates that MAIT cells are exhausted and pro-tumor in HCC." (PMID 36551916, 2022). "GZMB+ Tregs could induce the apoptosis of effector T cells and were related to immune homeostasis and mediating tumor immunity." (PMID 35474948, 2022).
tumor (continued). "Another finding from this study was that combining high doses of ascorbate with ani PD-1 significantly increased Tc and macrophage infiltration in the tumor microenvironment and increased IL-12 production, increased Tc and NK activation, and increased granzyme B production." (PMID 36072595, 2022). "We hypothesized that consideration of activated, GZMB expressing T lymphocytes complemented with M1 polarized macrophages might reflect more precisely the actual state of tumour recognition and the quality of the antitumour immune response." (PMID 36114487, 2022). "After activation, NK cells can release perforin and granzyme B to directly induce tumor cell death." (PMID 36505462, 2022). "The active granzyme B in the extracellular tumor microenvironment is dynamic, and variation in GZB levels might be due to timing rather than downregulation of GZB expression." (PMID 35890355, 2022). "Consequently, S1 + S2 stimulated OT-II CD4+ T cells were able to lyse B16-OVA tumor cells in vitro when cultured in Th1 media in a GzmB and MHC II dependent manner." (PMID 36241639, 2022). "publicized that gasdermin E could trigger caspase-independent pyroptosis in cancer cells through suppressing tumor growth by granzyme B in killer cells." (PMID 36177039, 2022). "The results showed that α5-nAChR knockdown promoted granzyme B secretion in tumour tissues." (PMID 35971127, 2022). "Furthermore, Granzyme B has the ability to remodel the extracellular matrix by inducing anoikis and detachment of tumor cells, which prevents tumor cell migration and invasion." (PMID 35300331, 2022). "Thus, we performed ELISA to estimate the fraction of granzyme B in the tumor versus circulation of tumor-bearing mice." (PMID 35788116, 2022). "Recent findings have shown the importance of Granzyme B (GzmB) in regulatory immune cells, which may contribute to tumor growth and immune evasion during cancer development." (PMID 35326588, 2022). "However, compared to MDSCs from the tumor-bearing control group, MDSCs in the cryo-thermal therapy group significantly decreased Th1 differentiation and inhibited the expression of granzyme B in CD4+ T cells." (PMID 36389684, 2022). "Notably, the infiltrative B cell follicles showed higher markers of proteins associated with effective anti-tumor immune responses (CD8, Granzyme B)." (PMID 36052068, 2022). "Moreover, patient P015 who received multiple RFA treatments, and two batches of vaccines showed more granzyme B in post-vaccination tumor tissue, indicating the better infiltration activity of T cells upon vaccination." (PMID 36248865, 2022). "Furthermore, activated DC1 can directly kill tumor cells through tumor necrosis factor-related apoptosis-including ligand (TRAIL) and Granzyme B-dependent mechanisms causing tumor regression." (PMID 35883639, 2022). "To investigate whether the expression of LINC01123, B7–H3, or miR-214-3p in HNSCC cells affects CD8+T-cell function, we analyzed the expression of TNF-α, IFN-γ, perforin, and granzyme B in the CD8+T cells by flow cytometry after coculture with the tumor cells." (PMID 35115487, 2022). "BRB-E administration in carcinogen-induced mice attenuates the differentiation and infiltration of Tregs to the tumor site, limiting the immunosuppressive microenvironment, and is associated with an increased presence of antitumoral CD8+ T cells and enhanced Granzyme B production." (PMID 36016924, 2022). "Chang’s study revealed that CD4+CD25+ Treg cells in the TME might rely on granzyme B and perforin to eliminate CD8+ effector T cells, resulting in a loss of function to help tumor cells escape from the toxic effect of CD8+ effector T cells." (PMID 36553542, 2022). "Interestingly, IF analyses of MTP-treated tumors confirmed a significant increase of tumor-infiltrating NK cells expressing granzyme B." (PMID 36397148, 2022).
tumor (continued). "However, when pancreatic tumor cells are co-cultured with purified, expanded γδ T cells and neutrophils, tumor cell lysis is increased compared to co-culture with γδ T cells alone, which can be attributed to elevated granzyme B and IFN-γ production." (PMID 35880177, 2022). "B cells act as antigen-presenting cells to present tumor-associated antigen (TAA) to CD4+ T cells, and then help CD4+ and CD8+ T cells to secrete interferon-γ, resulting in immediate cytotoxicity to tumor cells; meanwhile, B cells directly lyse tumor cells by secreting granzyme B and TRAIL." (PMID 35563678, 2022). "However, PLAP CAR T cells need to be evaluated in terms of other anti-tumor factors, including perforin, granzyme B, and other factors, to more easily compare their cytotoxicity and activation with other CAR T-cell therapy studies." (PMID 36139135, 2022). "Granzyme B+ tumour-infiltrating cells could be involved in the inhibition of tumour progression in canine TCC." (PMID 35324835, 2022). "Subsequently, we tested whether 68Ga-grazytracer PET could be used to predict early tumor responses to ICI in animal models by targeting granzyme B released by effector T cells upon immune responses." (PMID 35788116, 2022). "Notably, both Kaede Green+ and Kaede Red+ CD8 T cells in the tumor showed a significant increase in the proportion expressing Granzyme B and IFNγ." (PMID 35472220, 2022). "Moreover, CTLs exert their anti-tumor effects through the introduction of granzyme B to the cytosol of target tumor cells and, therefore, induce rapid cell death." (PMID 36605208, 2022). "Notably, MTP treatment results in a significant increase in intratumoral DC and NK cells expressing granzyme B, and lead to the control of tumor growth in these aggressive NB mouse models." (PMID 36397148, 2022). "Furthermore, there was downregulated expression of TNF-α, IFN-γ, perforin, and granzyme B in the peripheral blood of tumor-bearing C3H mice in the sh-LINC01123 + miR-214-3p-inhibitor group (P < 0.05)." (PMID 35115487, 2022). "Granzyme B (GZMB) is a component of cytolytic granules within cytotoxic T lymphocytes (CTLs) and natural killer (NK) cells, which are involved in several pathologies, including the formation of the tumour microenvironment." (PMID 36601599, 2022). "Most importantly, the levels of total and activated CD8+ cytotoxic T cells (GzmB+) that infiltrated the tumor microenvironment increased, while the proportion of exhausted CD8+ T cells decreased, indicating that the deficiency of Tmub1 maintains high cytotoxic T lymphocyte activity." (PMID 36376293, 2022). "Moreover, secretion of IFN-γ and Granzyme B in infiltrated CD8+ T cells in the tumor microenvironment was also increased." (PMID 36230638, 2022). "An attractive immune-related biomarker, granzyme B secretion represents the final signal of multiple antitumor immune pathways, not only reflecting the localization of cytotoxic T cells in the tumor area, but also directly indicating the potential ability of cytotoxic T cells to kill tumor cells." (PMID 35788116, 2022). "Upon tumor establishment, characterization of the BM microenvironment revealed the expression of both activation and suppressive markers by lymphocytes, such as granzyme B and PD-1, respectively." (PMID 35874665, 2022). "Tumour uptake correlated with tumoural granzyme B expression in syngeneic mouse model." (PMID 36297474, 2022). "As a T cell activation marker, the expression of GZMB is important for tumor immunity." (PMID 36204682, 2022). "Additionally, both effector and memory B cells can perform direct anti-tumour functions via granzyme B and TRAIL, as demonstrated in human hepatocellular carcinoma." (PMID 35406451, 2022). "Furthermore, serpin B9 can promote tumour survival through inhibition of cancer cell-intrinsic granzyme B, which can become expressed in various malignancies." (PMID 35401556, 2022). "Activated T cells produce perforin and granzyme B, leading to cytolysis of tumor cells." (PMID 36159851, 2022).